PAM (peptidylglycine alpha-amidating monooxygenase)
Description:
Bifunctional enzyme that catalyzes amidation of the C-terminus of proteins. Alpha-amidation is present at the C-terminus of many endocrine hormones and neuropeptides and is required for their activity. C-terminal amidation also takes place in response to protein fragmentation triggered by oxidative stress, promoting degradation of amidated protein fragments by the proteasome. Alpha-amidation involves two sequential reactions, both of which are catalyzed by separate catalytic domains of the enzyme. The first step, catalyzed by peptidyl alpha-hydroxylating monooxygenase (PHM) domain, is the copper-, ascorbate-, and O2-dependent stereospecific hydroxylation (with S stereochemistry) at the alpha-carbon (C-alpha) of the C-terminal glycine of the peptidylglycine substrate. The second step, catalyzed by the peptidylglycine amidoglycolate lyase (PAL) domain, is the zinc-dependent cleavage of the N-C-alpha bond, producing the alpha-amidated peptide and glyoxylate. Similarly, catalyzes the two-step conversion of an N-fatty acylglycine to a primary fatty acid amide and glyoxylate (By similarity).
Synonyms: PHM; PAL; PAM-1
Tractability: Small molecule: a high-quality ligand is known; it belongs to a druggable protein family. Antibody: UniProt places it where antibodies can reach, with medium confidence; UniProt predicts a signal peptide or a membrane-spanning region; its Gene Ontology location is reachable by antibodies, with medium confidence. PROTAC: ubiquitination databases record sites on it; its protein half-life has been measured; a small molecule that binds it is known.
Target class: Enzyme
Gene: Protein-coding gene on chromosome 5 (102,753,981 to 103,031,149, forward strand). Ensembl gene ENSG00000145730.
Subcellular location: Cytoplasmic vesicle, secretory vesicle membrane; Membrane (Isoform 1); Membrane (Isoform 2); Secreted (Isoform 3); Secreted (Isoform 4)
Subcellular location (Human Protein Atlas): Cytosol; Golgi apparatus; Predicted to be secreted
Gene Ontology:
Molecular function: peptidylamidoglycolate lyase activity; peptidylglycine monooxygenase activity; protein binding; zinc ion binding; calcium ion binding; copper ion binding; catalytic activity; monooxygenase activity; oxidoreductase activity, acting on paired donors, with incorporation or reduction of molecular oxygen, reduced ascorbate as one donor, and incorporation of one atom of oxygen
Biological process: peptide amidation; protein maturation; response to zinc ion; cellular response to oxidative stress; fatty acid primary amide biosynthetic process; peptide metabolic process
Cellular component: extracellular exosome; membrane; extracellular region; secretory granule membrane; transport vesicle membrane
Genetic constraint (gnomAD): Loss-of-function variants: 18 observed, 30.94 expected, observed/expected ratio (o/e) 0.58, 90% interval 0.4 to 0.86. The upper end of that interval is the gene's LOEUF score, 0.86, which puts it in group 3 of 6, group 1 being the genes least tolerant of losing a copy. Missense variants: 376 observed, 449.32 expected, observed/expected ratio (o/e) 0.84, 90% interval 0.77 to 0.91. Synonymous variants: 143 observed, 166.09 expected, observed/expected ratio (o/e) 0.86, 90% interval 0.75 to 0.99.
Homologues: Orthologues: chimpanzee PAM (99% identical), macaque PAM (98% identical), pig PAM (93% identical), guinea pig PAM (92% identical), rabbit PAM (91% identical), dog PAM (90% identical), rat Pam (90% identical), mouse Pam (81% identical), tropical clawed frog pam (68% identical), zebrafish pam (55% identical), Drosophila melanogaster Pal1 (19% identical), Drosophila melanogaster Pal2 (15% identical), and 1 more.
Diseases named in the same sentence as PAM in open-access papers:
PAM is named in the same sentence as 16 diseases in open-access papers, as found by Europe PMC text mining. Sharing a sentence is not in itself a finding about the gene and the disease. The quoted sentences say what the papers report.
diabetes (2 papers, 2021 to 2023). "“Tier 2” additionally includes four genes within the top 50 genes and either being causal for monogenic diabetes or harboring causal coding variants of T2D35 (GCK, SLC30A8, ABCC8, and PAM)." (PMID 37292813, 2023). "The “β-cell-related” gene group includes SLC30A8, SIX3, and PAM, genes involved in pancreatic β-cell function but not monogenic diabetes." (PMID 37292813, 2023).
glioma (1 paper, 2020). A benign or malignant brain and spinal cord tumor that arises from glial cells (astrocytes, oligodendrocytes, ependymal cells). "CAMK2D, EIF3K, MPC2, MYL12B, PAM, and SLC35B4, selected from the schizophrenia dataset and TCGA, were reevaluated in CGGA through gene expression in glioma grading and survival curves between patients having high level of gene expression and those having low level of gene expression." (PMID 32565801, 2020).
ovarian disorder (1 paper, 2024). A disease involving the ovary. "Our findings revealed distinct cargo compositions in enhanced exosomes, featuring upregulated proteins such as EFEMP1, HtrA1, PAM, and SDF4, suggesting their potential for treating ovarian disorders." (PMID 38793064, 2024).
pituitary adenoma (1 paper, 2026). "Potential associations include variants in emerging pituitary adenoma predisposition genes, including NF1, PRKACB, PAM, and CHEK2." (PMID 41965096, 2026).
somatotrophinoma (1 paper, 2023). "Germline loss-of-function variants in PAM, encoding peptidylglycine α-amidating monooxygenase (PAM), were recently discovered to be enriched in conditions of pathological pituitary hypersecretion, specifically: somatotrophinoma, corticotrophinoma, and prolactinoma." (PMID 38075079, 2023).
type 2 diabetes (1 paper, 2023). "Of the 132 type 2 diabetes Knowledge Portal effector genes, we identified 18 (14%) as candidate effector genes for at least one phenotype, including ABCC8, KCNJ11, NKX2–2, G6PC2, PAM, HNF4A, SLC30A8, RFX6, PCSK1, and GLIS3." (PMID 37333221, 2023).
tumor (3 papers, 2022 to 2023). "In contrast, patients with insufficient expression of SORBS2, PAM, ZFAT, DOCK7, ERMAP, BTF3, and GUSB in the tumor tissues had shorter survival duration than patients in the high-expression group." (PMID 37315301, 2023). "We found that the RNA expression levels of PDLIM3, PAM, PDLIM7, FSCN1 and LGALS3 were significantly upregulated in tumor samples, which provides ideas for further studies." (PMID 36177006, 2022).
PAM also shares sentences with these, for which no sentence is quoted: aneurysm (1 paper); cardiovascular disease (1); gastric cancer (1); heart failure (1); Hypertension (1); Insulin resistance (1); maturity-onset diabetes of the young (1); schizophrenia (1); uveal melanoma (1).